ANXA1 (annexin A1)
Description:
Plays important roles in the innate immune response as effector of glucocorticoid-mediated responses and regulator of the inflammatory process. Has anti-inflammatory activity. Plays a role in glucocorticoid-mediated down-regulation of the early phase of the inflammatory response (By similarity). Contributes to the adaptive immune response by enhancing signaling cascades that are triggered by T-cell activation, regulates differentiation and proliferation of activated T cells. Promotes the differentiation of T cells into Th1 cells and negatively regulates differentiation into Th2 cells. Has no effect on unstimulated T cells. Negatively regulates hormone exocytosis via activation of the formyl peptide receptors and reorganization of the actin cytoskeleton. Has high affinity for Ca(2+) and can bind up to eight Ca(2+) ions (By similarity). Displays Ca(2+)-dependent binding to phospholipid membranes. Plays a role in the formation of phagocytic cups and phagosomes. Plays a role in phagocytosis by mediating the Ca(2+)-dependent interaction between phagosomes and the actin cytoskeleton (By similarity). In the context of antitumor immunity, interacts with FPR1 on dendritic cells allowing for tumor-associated antigens uptake and cross-presentation to T cells to mount an antitumor specific T cell response. [Annexin Ac2-26]: Functions at least in part by activating the formyl peptide receptors and downstream signaling cascades. Promotes chemotaxis of granulocytes and monocytes via activation of the formyl peptide receptors. Promotes rearrangement of the actin cytoskeleton, cell polarization and cell migration. Promotes resolution of inflammation and wound healing. Acts via neutrophil N-formyl peptide receptors to enhance the release of CXCL2.
Synonyms: ANX1; LPC1
Tractability: Antibody: UniProt places it where antibodies can reach, with high confidence; its Gene Ontology location is reachable by antibodies, with high confidence; the Human Protein Atlas places it where antibodies can reach. PROTAC: UniProt records ubiquitination sites on it; ubiquitination databases record sites on it; its protein half-life has been measured.
Target class: Ion channel; Annexin; Other ion channel
Gene: Protein-coding gene on chromosome 9 (73,148,874 to 73,170,629, forward strand). Ensembl gene ENSG00000135046.
Subcellular location: Nucleus; Cytoplasm; Cell projection, cilium; Cell membrane; Membrane; Endosome membrane; Basolateral cell membrane; Apical cell membrane; Lateral cell membrane; Secreted; Secreted, extracellular space; Secreted, extracellular exosome; Cytoplasmic vesicle, secretory vesicle lumen; Cell projection, phagocytic cup; Early endosome; Cytoplasmic vesicle membrane
Subcellular location (Human Protein Atlas): Cytosol; Plasma membrane; Nucleoplasm; Predicted to be secreted
Pathways (Reactome):
Signal Transduction: Formyl peptide receptors bind formyl peptides and many other ligands; G alpha (i) signalling events; G alpha (q) signalling events
Developmental Biology: Developmental Lineage of Pancreatic Ductal Cells
Immune System: Interleukin-4 and Interleukin-13 signaling
Muscle contraction: Smooth Muscle Contraction
Gene Ontology:
Molecular function: cadherin binding involved in cell-cell adhesion; calcium ion binding; calcium-dependent phospholipid binding; calcium-dependent protein binding; lipid binding; phospholipase A2 inhibitor activity; protein binding; phosphatidylserine binding; phospholipid binding; signaling receptor binding; phospholipase inhibitor activity
Biological process: actin cytoskeleton organization; cellular response to glucocorticoid stimulus; cellular response to vascular endothelial growth factor stimulus; G protein-coupled receptor signaling pathway, coupled to cyclic nucleotide second messenger; granulocyte chemotaxis; keratinocyte differentiation; monocyte chemotaxis; negative regulation of exocytosis; negative regulation of interleukin-8 production; negative regulation of T-helper 2 cell differentiation; neutrophil activation; neutrophil clearance; neutrophil homeostasis; peptide cross-linking; positive regulation of cell migration involved in sprouting angiogenesis; positive regulation of interleukin-2 production; positive regulation of T cell proliferation; positive regulation of T-helper 1 cell differentiation; positive regulation of vesicle fusion; positive regulation of wound healing; regulation of cell shape; regulation of hormone secretion; alpha-beta T cell differentiation; cell surface receptor signaling pathway; inflammatory response; and 10 more
Cellular component: actin filament; adherens junction; cell surface; cornified envelope; cytoplasm; cytosol; endosome; extracellular exosome; extracellular matrix; extracellular region; focal adhesion; membrane; nucleoplasm; nucleus; plasma membrane; vesicle; apical plasma membrane; basolateral plasma membrane; cytoplasmic vesicle membrane; early endosome; early endosome membrane; endosome membrane; lateral plasma membrane; motile cilium; vesicle membrane; and 4 more
Genetic constraint (gnomAD): Loss-of-function variants: 25 observed, 29.55 expected, observed/expected ratio (o/e) 0.85, 90% interval 0.62 to 1.18. The upper end of that interval is the gene's LOEUF score, 1.18, which puts it in group 5 of 6, group 1 being the genes least tolerant of losing a copy. Missense variants: 320 observed, 311.61 expected, observed/expected ratio (o/e) 1.03, 90% interval 0.94 to 1.13. Synonymous variants: 102 observed, 109.08 expected, observed/expected ratio (o/e) 0.94, 90% interval 0.8 to 1.1.
Homologues: Orthologues: chimpanzee ANXA1 (99% identical), macaque ANXA1 (95% identical), dog ANXA1 (91% identical), pig ANXA1 (90% identical), guinea pig ANXA1 (89% identical), rat Anxa1 (89% identical), rabbit ANXA1 (88% identical), mouse Anxa1 (88% identical), tropical clawed frog anxa1 (67% identical), zebrafish anxa1a (64% identical), zebrafish anxa1b (51% identical), zebrafish anxa1d (51% identical), and 3 more. Paralogues in human: ANXA2 (51% identical), ANXA3 (46% identical), ANXA11 (45% identical), ANXA7 (43% identical), ANXA4 (42% identical), ANXA6 (42% identical), ANXA8 (40% identical), ANXA8L1 (40% identical), ANXA13 (40% identical), ANXA5 (40% identical), ANXA10 (37% identical), ANXA9 (33% identical).
Diseases named in the same sentence as ANXA1 in open-access papers:
ANXA1 is named in the same sentence as 411 diseases in open-access papers, as found by Europe PMC text mining. Sharing a sentence is not in itself a finding about the gene and the disease. The quoted sentences say what the papers report.
breast carcinoma (145 papers, 2008 to 2025). "The findings of this study highlight the potential role of ANXA1 in mediating resistance to PD‐1/PD‐L1 therapy in breast cancer, which is associated with MHC‐II expression." (PMID 40744683, 2025). "Seventy-three downregulated and seven upregulated genes were identified, with EGFR and ANXA1 identified as the pivotal genes associated with breast cancer progression." (PMID 38794206, 2024). "The results of the study indicate that uEVs, which contain ECM1 and ANXA1, have the potential to be used as diagnostic biomarkers for breast cancer." (PMID 39040439, 2024). "There are some known factors associated with the activation of ANXA1 expression and their implications in breast cancer." (PMID 37507468, 2023). "In breast cancer cells, nuclear localization of ANXA1 was associated with protection against heat-induced DNA damage." (PMID 37373303, 2023). "In MCF-7 breast cancer cells, the loss of ANXA1 upon stress led to an increased susceptibility to DNA damage and mutation." (PMID 37373303, 2023). "Estrogen, a pivotal hormone in breast cancer development, is implicated in the modulation of ANXA1 expression." (PMID 37507468, 2023). "In breast cancer cells, high levels of ANXA1 have been linked with changes in the tumor microenvironment via altering the inflammatory response of tumor-associated macrophages." (PMID 35008958, 2022). "We previously reported that the high expression of ANXA1 is significantly associated with inflammation, angiogenesis, and mast cell infiltration in breast cancer using in silico analyses." (PMID 33804148, 2021). "ANXA1 has been reported to be associated with resistance to tamoxifen in estrogen receptor-positive recurrent breast cancer and trastuzumab resistance in HER-2 positive breast cancer." (PMID 34238922, 2021). "We previously reported that ANXA1 high breast cancer was significantly associated with high infiltration of mast cells." (PMID 33804148, 2021). "In breast cancer, ANXA1 overexpression is associated with resistance against 5-FU and trastuzumab treatments." (PMID 33959206, 2021). "Nevertheless, an association was depicted between ANXA1 expression and breast cancer mortality and relapse." (PMID 33276477, 2020). "Clinical macro data confirmed that elevated ANXA1 expression was significantly associated with higher pathological grades and worse breast cancer-associated survival." (PMID 32226772, 2020). "Linear peptide antigen from ANXA1 analyzed by enzyme-linked immunosorbent assay (ELISA) showed a significant increase in antibody levels in lung and breast cancer." (PMID 33261560, 2020). "We have previously demonstrated that TNBC cases with high ANXA1 protein expression were associated with aggressive features of breast cancer." (PMID 31461932, 2019). "High expression of ANXA1 promotes metastasis of basal-like tumors and associates with poor prognosis in this breast cancer subtype." (PMID 29971090, 2018). "Recently, annexin A1 was implicated in the constitutive activation of NFκB in breast cancer to promote metastasis." (PMID 29462943, 2018). "In breast cancer, ANXA1 can also be associated with NF-κB, increases c-Myc activity, leading to the inhibition of miR196a transcription and promotes breast cancer migration and metastasis." (PMID 30213113, 2018). "Evidence has shown AnxA1, AnxA2, AnxA8 are associated with the basal-like phenotype and potentiates poor prognosis of basal-like breast cancer." (PMID 29416802, 2018). "This agrees with previous literature where reduced Annexin A1 expression was significantly associated with advanced breast cancer." (PMID 28910304, 2017). "Our data highlight reorganization of cellular structural components and rewiring of signaling networks upon loss of ANXA1 that partly explain the broad spectrum of roles proposed for ANXA1 in breast cancer." (PMID 29233185, 2017).
breast carcinoma (continued). "We compared annexin A1 and A2 protein expression, both of which are important regulators of normal breast cell physiology, breast cancer progression and are associated with more aggressive and invasive cancer phenotypes." (PMID 28068434, 2017). "Over the years, many potential biomarkers have been revealed to be of diagnostic value in breast cancer, such as serum angiopoietin-2, annexin A1, and miR-22." (PMID 28523467, 2017). "In general, ANXA1-positive cases have been associated with clinically aggressive basal-like breast cancer." (PMID 29233185, 2017). "Loss of annexin A1 has been associated with malignant transformation in ER+ breast cancer, and, conversely, recent reports associate high annexin A1 expression with cellular invasion in ER-." (PMID 28068434, 2017). "Our previous quantitative profiling of protein abundances in ANXA1+/− and ANXA1−/− murine mammary gland epithelial cells implicated a role for ANXA1 in breast cancer initiation and progression." (PMID 29233185, 2017). "We have previously reported through microarray studies that ANXA1 can inhibit the expression of multiple miRNAs, and in this study we investigated the association between miR-196a and ANXA1 and their relevance to breast cancer cell proliferation and growth." (PMID 27105503, 2016). "Though association of CALD1 to breast cancer therapy outcome has been poorly assessed so far, ANXA1 expression was previously associated to BRCA1/2 mutation carriers and prediction of high mortality risk in Her2+ patients." (PMID 26657294, 2016). "Similar findings were reported before as ANXA1 has been shown to be associated with increased metastatic potential in MCF-7 breast cancer cell lines following downregulation of ER and the expression of basal markers (e.g. vinculin)." (PMID 26657294, 2016). "This annexin-AMPK-mTOR-cell migration axis that we have described in here potentially explains the association between high annexin A1 levels and poor breast cancer prognosis in basal like breast cancer." (PMID 26000884, 2015). "Previous research using tissue microarray analysis has shown that in some breast cancers, ANXA1 loss leads to faster tumour growth and cancer progression." (PMID 26358523, 2015). "We found a significantly higher expression of ANXA1 in tumors from familial breast cancer patients with BRCA1/2 mutations compared with hospital and population-based breast cancer series." (PMID 26137966, 2015). "By mining the Cancer Genome Atlas (TCGA)-Breast Cancer dataset and manipulating annexin A1 levels in breast cancer cell lines, we studied the role of annexin A1 in breast cancer and underlying signaling pathways." (PMID 26000884, 2015). "ANXA1 being also expressed in normal myoepithelial cells, the loss of ANXA1 expression in breast carcinomas has been described as a stage of malignant transformation." (PMID 26137966, 2015). "ANXA1 is overexpressed in familial breast cancer patients with BRCA1/2 mutations and correlated with poor prognosis features: triple negative and poorly differentiated tumors." (PMID 26137966, 2015). "WalBC cells showed regulated expression of DSP, s100A14 and ANXA1 which are genes associated with well-differentiated, epithelioid breast cancer cell lines with weak invasive potential and poorly invasive tumors." (PMID 18179684, 2008). "Furthermore, ANXA1 has been implicated in enhancing Treg function and is associated with poor survival in breast cancer patients." (PMID 41267080, 2025). "Our results suggest that ECM1 and ANXA1 in uEVs could potentially serve as diagnostic biomarkers for breast cancer." (PMID 39040439, 2024). "Therefore, our study presents novel insights into the therapeutic potential of BF by highlighting their unexplored interaction with ANXA1, thus contributing to a deeper understanding of the molecular mechanisms underlying breast cancer progression." (PMID 37507468, 2023).
breast carcinoma (continued). "Furthermore, AnxA1 has been associated with poorly differentiated breast cancers, correlating with lower survival rates." (PMID 34571894, 2021). "Since the functions of ANXA1 and mast cells vary in different cancer types, the association between ANXA1 expression and mast cells may differ between breast cancer and PC." (PMID 33804148, 2021). "Along these lines, AnxA1-deficient mice displayed reduced breast cancer growth and enhanced survival, and it was proposed that AnxA1 binding to FPR2 on macrophages, influencing their polarization and infiltration of solid tumours, would be the underlying cause for enhanced tumour progression." (PMID 33810523, 2021). "We previously published that ANXA1 expression was associated with angiogenesis in breast cancer and that the abundance of mature blood vessels was associated with better survival; thus, it was of interest whether this was the case in PC." (PMID 33804148, 2021). "We reported that ANXA1 high breast cancer is associated with a high infiltration of mast cells." (PMID 33804148, 2021). "However, our group previously reported that ANXA1 high breast cancer was significantly associated with inflammation and angiogenesis signaling pathways." (PMID 33804148, 2021). "In breast cancer, ANXA1 expression is associated with BRCA1/2 mutations." (PMID 27941907, 2016). "ANXA1 might be a biomarker candidate for breast cancer survival prediction in high risk groups such as HER2+ cases." (PMID 26137966, 2015). "Our survival analysis showed that ANXA1 expression in breast tumors might be a biomarker candidate for breast cancer outcome prediction in high risk groups such as HER2+ cases, playing a complex role in chemotherapy resistance." (PMID 26137966, 2015). "ANXA1 expression has also been found to be associated with a highly invasive basal-like breast cancer subtype and to promote metastasis formation by enhancing the TGFβ/Smad signalling pathway, which in turn facilitates an epithelial mesenchimal transition switch." (PMID 26358523, 2015). "In breast cancer, the loss of ANXA1 expression is associated with poorer global survival rates." (PMID 24782913, 2014). "Interestingly, loss of ANXA1 expression has also been described in some tumors, for example, in breast cancer, cholangiocarcinoma, and gastric cancer." (PMID 25038797, 2014). "The ANXA1–FPR2 axis between tumor cells and TAMs may enhance cancer cell growth and migration by promoting M2-type polarization of TAMs, and furthermore, the ANXA1-deficient breast cancer mouse model showed enhanced survival due to increased M1 TAMs within the tumor environment." (PMID 35669791, 2022). "Phosphoproteomics from AnxA1-deficient mammary gland epithelial cells identified up- and downregulation of several signaling pathways that modulate cell motility and could contribute to breast cancer initiation." (PMID 33810523, 2021). "Our survival analysis of 890 TCGA breast cancer patient samples revealed that amongst the 139 patients with basal-like breast cancer tumors, high annexin A1 mRNA expression was associated with significantly shorter 5-year overall survival than patients with low annexin A1 expressing basal tumors." (PMID 26000884, 2015). "Targeting ANXA1 has been shown to diminish Treg function and reduce tumor size in breast cancer models." (PMID 41267080, 2025). "In breast cancer, ANXA1 has been described as both a tumor suppressor and an oncogene, with its expression levels depending on the molecular subtype." (PMID 40361334, 2025). "Estrogen receptor-positive breast cancers usually have low ANXA1 levels, while basal-like breast cancers show high ANXA1 expression, with both scenarios promoting tumor development in the corresponding tumor subtype." (PMID 40361334, 2025). "Our analysis of the TCGA‐BRCA breast cancer database revealed a significant differential expression of ANXA1 between normal and cancerous breast tissues, with ANXA1 being notably downregulated in cancer tissues (p < 2e−16)." (PMID 40744683, 2025).